CD86 (CD86 molecule)
Diseases named in the same sentence as CD86 in open-access papers (continued):
Sharing a sentence is not in itself a finding about the gene and the disease.
infection (continued). "(B) Quantitative representation of flow cytometric analysis of alteration in M1 CD86-positive population in STM-infected samples in comparison to uninfected (UI) and paraformaldehyde-fixed (PFA) bacteria at the indicated time post-infection." (PMID 39693143, 2024). "rBCG-Rv1002c infection significantly upregulated immune regulatory molecules on the macrophage surface, including CD40, CD80, CD86, and MHC-II." (PMID 38932351, 2024). "As for some DZ signature genes, the LZ biomarker CD83 is downregulated upon infection in ensemble experiments but retained in EBV+ subsets co-expressing BCL2A1 (BFL-1) and other GC LZ hallmarks (CD80, CD86, and MYC)." (PMID 38059622, 2024). "Next, we further analyzed the DEGs in dMφ subsets (TNF+dMφ, CD86+dMφ, CD163+dMφ, and TGFβ+dMφ) after infection." (PMID 38730500, 2024). "CD86 expression was increased in CD8α- and pDCs in both PEP-WT and PEP-619WW mice following infection." (PMID 38512979, 2024). "Increased mean fluorescence intensity (MFI) of CD86, MHC-II and CD70 was observed upon overnight incubation of infected DCs with TVH and depending on TCID50 used for infection." (PMID 36997583, 2023). "Although the proportion of CD80+CD86+ B cells increased, class switching failure appeared in SFTSV infection patients." (PMID 37033979, 2023). "On the other hand, infection with all GBS isolates significantly increased the expression of macrophage co-stimulatory molecules, CD80 and CD86 (middle and right)." (PMID 37213504, 2023). "We observed that upon BPM treatment, the innate cells expressing co-stimulatory and activation markers, such as CD80, CD86, and CD40, were enhanced at the primary site of infection, i.e., lungs." (PMID 37272833, 2023). "Depicting PCA of many factors in a circle of correlation, we tested if there are correlations between infection rate, ciliated cells, ACE2 positivity, CD86 positivity, and possibly age (warm colors and length of arrows that point in the same direction)." (PMID 36827975, 2023). "Within two days of type I IFN-induced CD69 expression, infection of B cells within mediastinal lymph nodes induces upregulation of CD69 and the co-stimulatory surface molecule CD86, thereby regulating B cell egress from lymph nodes into the bloodstream." (PMID 38203508, 2023). "Upon infections in vivo we found trogocytosis of CD80 and CD86 to predominantly occur in lymphatic organs, suggesting that the fate-separating effects of CD28 and CTLA4 on trogocytosed ligands regulate T cell behavior at these sites." (PMID 36309492, 2022). "After infection of murine bone marrow-derived DCs, increased expression of MHC class I and class II as well as CD86 was shown." (PMID 35615366, 2022). "The marked increase in B cell recruitment observed in response rhMPV-ΔG infection was paralleled by an upregulation of the activation markers CD69 on day 9 p.i. and CD86 on days 7 and 9 p.i., compared to rhMPV -WT infection." (PMID 35958551, 2022). "In vitro infection of isolated human dendritic cells with Y enterocolitica induced maturation, indicated by upregulation of CD83 and CD86, but downregulated MHC II expression and impaired T cell proliferation up to 6 days post-infection." (PMID 36504866, 2022). "After poly I:C treatment and seven days of CB4 infection, APCs (CD11b+CD11c+, CD11b+CD11c-) isolated from PLNs and spleens of MDA5+/- mice express similar levels of CD40 and CD86 compared to untreated CB4-infected MDA5+/- mice." (PMID 34804036, 2021). "Consonant with the prediction of the DYNAMO algorithm, infection with the seasonal IAV strains resulted in lower expression of HLADR (Signal 1) and CD86 (Signal 2) in comparison with infection with the pandemic strain." (PMID 34335598, 2021). "S. Typhimurium-infected chMoDCs showed significant upregulation in the expression of costimulatory (CD40, CD80, CD83 and CD86) and MHC molecules at 6 h post-infection in comparison to S. Gallinarum." (PMID 34446765, 2021).
infection (continued). "Another key observation is that after 10 months post-infection, the frequency and absolute counts of activated B cells (CD80+/CD86+) were higher in convalescent individuals." (PMID 35069575, 2021). "The frequency of activated CD11c+ cells co-expressing CD86 and MHC-II was elevated in the draining LN and lungs on day 7 post-infection relative to day 1 post-infection, returning to mock PBS infected levels." (PMID 34436169, 2021). "Using a HAdV-C5 chimera vector with the fiber knob of HAdV-B3 that bound to CD80 or CD86 instead of CAR, enhanced infection of these glioma cells." (PMID 32957644, 2020). "The expression of MHC II, CD40, and CD86 in Fo B cells and plasmablasts was significantly decreased in TNF-/- mice at week 3 after infection." (PMID 32742607, 2020). "Confirming data with in vitro infection of BMDCs with mOVA2, local DCs acquired maturation markers (CD40 and CD86), with CD40 being the most responsive." (PMID 31988324, 2020). "The increased expression of CD40, CD54, CD80, CD86, and MHCII in DC2.4 dendritic cell line has been reported after infection with M. smegmatis and M. bovis BCG expressing an epitope from ovalbumin." (PMID 33260418, 2020). "Mean fluorescence intensity signifying the estimate of surface expression of CD80, CD86, CD40, MHC I, and MHC II on macrophages increased significantly upon infection with Ms_Rv1954A as compared to Ms_Vc." (PMID 33163415, 2020). "CD86, a costimulatory molecule for T cells, was significantly upregulated in HLA-DRbright DCs after MVA infection of whole blood from HIV-ART patients." (PMID 33013882, 2020). "Infection of BMDM with live PS-sensitized (black bar) and WT Lb (dark gray bar) elevated the MFI of both CD40 and CD86 molecules above the ground levels of BMDM alone (light gray) and those light-exposed (blank)." (PMID 33051524, 2020). "Similarly, while steady state levels of CD86 and CD80 on splenic cDCs derived from WT and BCAP-deficient mice were comparable, their expression on splenic cDCs from BCAP-deficient mice were much higher than that from WT mice following infection with Escherichia coli DH5α." (PMID 32133012, 2020). "In the blocked group, BMDC surface markers CD80, CD86, and MHC class II were significantly reduced in comparison with the infection group." (PMID 30791397, 2019). "Cell surface expression of CD206, CD86, and CD64 was monitored by flow cytometry in mock- and C. trachomatis-infected cells at 0, 24, and 48 h post-infection." (PMID 31134002, 2019). "As the cells are infected by SFTSV, CD86 expression decreases and CD206 increases as the infection proceeds from 24 to 48 h, as evidenced by both flow cytometric analysis and IF staining." (PMID 31156641, 2019). "For instance, the infection of human moDCs with L. amazonensis downregulates the expression of CD80 and upregulates the expression of CD86, which is followed by a decrease in IL-6 production during DC differentiation." (PMID 30873156, 2019). "CD86 and CD64 expression remained steady in infected CA mφ, with very little change across all time points post-infection." (PMID 31134002, 2019). "The infection group showed a notable increase in the expression of CD40, CD80, CD86, and MHC class II." (PMID 30791397, 2019). "Increased CD86 expression has been observed in a somewhat similar chronic, hepatotropic infection with HBV, where liver lobules were found to have a higher total count and percentage of CD86+ macrophages, compared to CD80+ or PD-L1+ macrophages." (PMID 31027182, 2019). "As observed in vaccinees, YF-17D infection of PBMCs also induced upregulation of activation markers on various immune cells, including CD80 and CD86 on myeloid DCs (mDCs) and CD54 and CD69 on monocytes." (PMID 31285858, 2019). "MHC class II and costimulatory CD86 were found on cDC and Gr-1intCD11bhiCD11cint M-MDSC from PBS-treated control mice and were upregulated upon MAA infection." (PMID 30386330, 2018).
infection (continued). "Though still showing larger CD86 expression than PBS immunized mice, deficiencies in co-stimulatory molecule expression compared to wild type immunization could contribute to impaired protective immunity during infection with necrosis-inducing L. monocytogenes." (PMID 29324702, 2018). "MSP121-specific AMB sorted during chronic P. chabaudi infection, and MSP121-specific Bmem sorted after resolution of the infection shared the expression of a series of mouse memory markers, including Cd80, Fcrl5, Nt5e (CD73), and Cd86." (PMID 30387712, 2018). "All NPs-treated HSV-2 retained CD86 expression and down-regulated CD80 expression in comparison to infection with live HSV-2." (PMID 29872440, 2018). "In accordance, CD14+ cells strongly upregulated CD86 during infection with HTNV and high levels of soluble CD86 were detected in hantavirus-infected patients." (PMID 30559738, 2018). "In fresh whole blood, less than 1% of pDC expressed CD86, CD40 or CD80 before infection or at peak parasitaemia." (PMID 28572564, 2017). "Thirty days post infection, the cell populations expressing MHC class II, IL-4R and Dectin-1 were increased, but those expressing the costimulatory receptor CD86, and MR or CD23 were reduced." (PMID 29156562, 2017). "pDC remained responsive to TLR stimulation, producing IFN-α and upregulating HLA-DR, CD86, CD123 at peak-infection." (PMID 28572564, 2017). "Consistent with this, both ΔN146 infection and LPS treatment dramatically stimulated the expression of CD40 and CD86 as indicated by enhanced fluorescence intensities." (PMID 28150813, 2017). "In our previous study, we observed that infection by L. amazonensis in addition to decrease CD40 expression, also inhibited the expression of MHCII and CD86." (PMID 28791011, 2017). "Infection of the human monocytic cell line U937 with primary isolates of an Indian HIV-1 subtype C induced the downregulation of CD80 and CD86." (PMID 29023371, 2017). "At day 3 post infection, MHC I expression increased on B cells in MLN and PLN of NOD mice, and CD86 expression increased in MLN." (PMID 27405244, 2016). "In our ex vivo studies, BMDC from RIG-I-/- mice showed lowered levels of CD86 and MHCII upregulation upon infection with IAV." (PMID 27438481, 2016). "The results revealed that the expression of CD11c, CD80, CD86, MHC class II, and CCR7 was increased 7 days post-infection." (PMID 27279150, 2016). "After infection with the H9N2 virus for 24 h, the CD86, CD80, and CD40 expression levels in the DCs were significantly increased compared to the untreated group." (PMID 27826541, 2016). "Splenic cDCs expressed significantly higher levels of CD40 during infection, however, consistent with previous work, MHC class II and CD86 expression remained unchanged compared with naive controls." (PMID 26657145, 2016). "Concerning infection with L. braziliensis, data from literature showed that CD14+ monocytes of peripheral blood from CL patients had a decreased expression of CD80 and CD86 following culture with media only or after restimulation with Leishmania antigen." (PMID 27536300, 2016). "The pDCs in PLN showed increased MHC I expression on days 3 and 4 post infection, decreased MHC II expression on days 4 and 5 and unaltered expression of CD80 and CD86." (PMID 27405244, 2016). "The results showed that the expression of CD86 and CD206 was significantly reduced at three days post-infection compared with that in the uninfected M0 cells." (PMID 26091535, 2015). "Since the CD86 and the MHC-II molecules are extremely necessary to antigen presentation, it is likely that the MФ resulting from the infection with N. gonorrhoeae have a poor proliferative capacity over T cells." (PMID 26125939, 2015). "Taken together, our results show that infection of human cells with the Col cl1.7 leads to a higher expression of CD80 and CD86, as well as of IL-17, favoring monocyte activation." (PMID 26147698, 2015).
infection (continued). "ALE (200 mg/kg bw) elevated CD80 and CD86 expression profile to 55.5% (P < 0.001) and 28.8% (P < 0.001), respectively in comparison with infection control (CD80 = 34.9%, CD86 = 13%)." (PMID 25884649, 2015). "We further find that DENV infection blocked the expression of activation markers CD80 and CD86 on monocytes, DCs and MΦs in the dermis and that this effect was more pronounced during ADE compared to 1° infection." (PMID 25474197, 2014). "In contrast, infection of BMDC from 5-LO−/− with L. infantum inhibits their activation, presenting reduced expression of CD86 surface markers." (PMID 25309905, 2014). "We asked about the age-dependent expression of the costimulatory molecules CD86, CD80 and CD70 on the surface of CD103+ and CD11b+ DCs in the MLN at three days post-infection with RSV as an indication of their capacity to effectively induce adaptive responses." (PMID 24550729, 2014). "Infection of Mo-DC with the cp strain of BVDV up-regulated expression, while infection with ncp strains of BVDV down-regulated expression of the cell surface markers MHCI, MHCII, and CD86." (PMID 24607146, 2014). "The down-regulation of CD86 in ncp BVDV1b-TGAN, ncp BVDV2a 28508-5 or ncp BVDV2a 1373 infected Mo-DC was significant at 48 hours post-infection as compare to their time point control." (PMID 24607146, 2014). "To assess the phenotypic changes induced by BCG-dHCM infection, we assessed the expression of MHC, CD86 and CD83 molecules on DC." (PMID 24690183, 2014). "The numbers of CD86+ CD4+ and CD8+ T cells increased during the course of infection, with maximal numbers around day 10 p.i.." (PMID 25144228, 2014). "To explore potential differential effects of the different PA strains on DC activation, we stained DCs for the activation markers CD86 and CD40 following infection with the different PA strains." (PMID 24587305, 2014). "Before infection, the immature DC phenotype (CD1a +, HLA-DR +, CD80 −, CD86 −, CD14 −, CD83−) was verified by flow cytometry (Figure A1)." (PMID 23970881, 2013). "For CD11b+ mononuclear cells, the total number of cells in the spleen was significantly increased by infection, as were the numbers of CD11b+ MHC II+ and CD11b+ CD86." (PMID 23556020, 2013). "At day 2 post-infection, we noted 18–19% increase on the percentage of CD80 and CD86 expression on WNV H8912-infected BMDCs when compared to WNV NY99-infected cells respectively (P<0.01)." (PMID 23785537, 2013). "Expression levels of CD86, CD80 and CD40 on mDCs were comparable between C3−/− and WT mice during the course of infection." (PMID 23326231, 2013). "A recent study showed, albeit for BCG, that MHC-II, CD80, CD86, and CD40 are down-tuned during chronic phase of infection." (PMID 22719245, 2012). "By 24 h, the infection induced significant recruitment and activation (enhanced expression of CD80, CD86 and MHC-II) of macrophages into bronchoalveolar spaces." (PMID 22768201, 2012). "Infection also induced the expression of co-stimulatory molecules such CD40, CD83, CD86, adhesion molecules (CD38, Itga5, and ICAM1), and tissue invasion molecules such as MMP12 and MMP14." (PMID 22928052, 2012). "Subsequent LVS infection, Acai PS enhanced surface expression of CD11b, CD40, CD80, CD86, TLR2, and MHC class II in a dose-dependent fashion, while TLR4 expression was downregulated in both mock- and LVS- infected macrophages." (PMID 22438809, 2012). "Following infection with HTLV-1, CD80 and CD86 are constitutively expressed suggesting that HTLV-1-infected CD80+/CD86+ T cells serve as antigen presenting cells, leading to a sustained proliferation of T cells." (PMID 21994790, 2011). "Infection during or after sensitization resulted in significant decreases in MHCII and CD86 expressing pDCs and mDCs compared to uninfected, allergic controls." (PMID 21998577, 2011). "Gating on the total MoDC population at 24 hr after infection, an infectious dose of MOI 0.05 induced CD86 and MHC-II expression significantly." (PMID 21771345, 2011).
infection (continued). "Our results indicate that following infection with RABV, IPS-1+/+ and IPS-1+/− BMDCs express high levels of CD86 on their surface." (PMID 20661430, 2010). "In comparison with the CD8− DC isolated from BCG infected mice iCD8− DC, the CD8+ DC isolated from the mice with the same infection iCD8+ DC expressed higher CD80 (65.66% vs 17.43%), CD86 (57.43% vs 30%) and CD40 (44% vs 35%) molecules." (PMID 20174628, 2010). "The transcript abundance of costimulatory molecules (such as CD86, ICOS), CAMs, and TCRs/CD3 complex as well as co-receptor molecules (such as CD8A, CD8B) was remarkably increased after infection with N-PRRSV." (PMID 20614006, 2010). "The DC activation statusafter infection was evaluated by assessing the expression of the co-stimulatory molecules CD80 and CD86, as well as by their capacity to present MHC class I and II restricted epitopes to OVA-specific CD8+ or CD4+ T cells, respectively." (PMID 20628596, 2010). "Although there is substantial expansion of DC numbers during infection, the CD86hi-CD8αint-CD11b− subset is markedly diminished, and expression levels of CD40, CD86 and CD103 are reduced." (PMID 19766674, 2009). "After infection, the percentages of CD80 and CD86 memory B-cells had decreased by factors of 2.2 and 2 by D14 p.i., by factors of 1.6 and 2.3 by D21 p.i. and by factors of 3 and 3.5, respectively, by D28 p.i.." (PMID 19543531, 2009). "CD80 and CD86 single-knockout mice are able to control MHV-68 infection, while CD80/CD86 double-knockout mice fail to maintain efficient long-term control of MHV-68, demonstrating that these molecules play overlapping roles in the control of MHV-68." (PMID 19621080, 2009). "In support of this, AM were only transiently and slightly activated, as measured by CD86 and CD40 expression, after infection with MA15." (PMID 19851468, 2009). "At 0, 12 and 18 h following infection, cells were harvested and stained with mAbs specific for CD40, CD86, CD80, and MHC class II I-Ad." (PMID 18412969, 2008). "DCs isolated from infected animals 12 and 20 days after infection, however, showed a reduced level of activation, with lower levels of CD40, CD80, CD86 and MHC class II molecules on their surface compared with DCs from uninfected animals." (PMID 16611373, 2006). "Monocyte HLA-DR and co-stimulatory molecules (CD80 and CD86), and an increase in soluble PD-L1, discriminate between critically ill patients, patients with mild infection, and patients with non-infectious illness." (PMID 41624862, 2026). "Upon infection with rRSV-A-0594-eGFP, the expression of CD86, but not that of CD80, was upregulated in eGFP+ PMs." (PMID 41280933, 2025). "Compared to the phosphate-buffered saline (PBS) and Adv-Ctrl groups, infection with Adv-NF and Adv-NGS at a MOI of 2 both resulted in a 2-fold expansion of CD80+CD86+ mouse DCs, demonstrating a potency comparable to that of lipopolysaccharide (LPS) stimulation." (PMID 40195559, 2025). "In our case, the expression of CD206 in the PEEK-PDA-Sr/AMP group was highest accompanied by a decrease in CD86 expression at 4 weeks postoperatively, suggesting that the potential of Sr/AMP co-modified PEEK can inhibit inflammatory infection response and enhance interfacial osseointegration." (PMID 40994673, 2025). "Infection with the Genotype II ASFV CN/GS/2018 strain downregulates CD86 expression in splenic monocytes and macrophages, while infection with genotype II ASFV-HLJ/18 strain upregulates CD86 expression in PAMs." (PMID 40817451, 2025). "The divergent correlation patterns of CD86 (negative in macrophages but positive in other cells) further highlighted macrophage-specific regulatory disruptions during infection." (PMID 40723441, 2025). "Although infection induced CD80, CD83, CD86, and HLA class II expression on the surface of DCs, the activation of CD4+ T cells was impaired, which is consistent with findings in RSV-infected murine DCs, where the formation of immunological synapses was impaired." (PMID 41280933, 2025).